MC4R (melanocortin 4 receptor)
Diseases named in the same sentence as MC4R in open-access papers (continued):
Sharing a sentence is not in itself a finding about the gene and the disease.
Obesity (continued). "Changes in endogenous cannabinoids (eCBs) signaling strength are inversely related to energy state, where impaired synthesis of 2-AG in MC4R neurons leads to weight loss, increased serum leptin sensitivity, reduced appetite, increased energy expenditure, and resistance to diet-induced obesity." (PMID 40130157, 2025). "For instance, like fellow genes associated with earlier age at onset of obesity such as MC4R and PCSK1, SLTM may affect neurohormonal pathways that were not directly tested by our functional assay." (PMID 40912257, 2025). "Similarly, MC4R polymorphisms, which are key regulators of appetite and energy expenditure, have been linked to impaired glycemic control alongside obesity." (PMID 40149950, 2025). "It remains unknown if MC4R is a viable target for improving the obesity-associated chemosensitivity observed in humans." (PMID 39542230, 2025). "At the same time, some secondary factors also contribute to the occurrence of high BMI such as polycystic ovary syndrome (PCOS), hypothyroidism, or genetic predispositions (e.g., gene variants such as FTO and MC4R, which are significantly associated with obesity risk)." (PMID 41334401, 2025). "Additionally, in a study of 25 patients with obesity from Guadeloupe, five heterozygous variants were identified in the MC4R, NTRK2, SH2B1, and SIM1 genes, with a frequency of approximately 10%." (PMID 40149731, 2025). "Furthermore, loss-of-function variants in BSN and APB1A have demonstrated markedly larger effects on obesity risk than those observed for variants in MC4R." (PMID 40523925, 2025). "The recent approval of Setmelanotide, an MC4R agonist, for treating obesity caused by deficiencies in proopiomelanocortin (POMC), proprotein convertase subtilisin/kexin type 1 (PCSK1), or Leptin Receptor, has heightened scientific interest in the effects of MCRs on feeding and energy balance." (PMID 39974186, 2025). "Variants in the MC4R gene are associated with a non-syndromic form of obesity that could explain the unusual macrocephaly and obesity." (PMID 39414991, 2025). "Loss of MRAP2 function leads to decreased MC4R signaling and obesity in mouse models." (PMID 39237720, 2025). "Clinical characteristics of MC4R pathway diseases associated with hyperphagia and obesity." (PMID 40528426, 2025). "However, only seven variants were shown to reduce αMSH-induced MC4R cAMP signaling, while some variants enhanced signaling, incongruous with known MC4R inactivation usually observed in obesity." (PMID 39807633, 2025). "The first study to functionally assess three MRAP2 variants identified in children with extreme obesity, showed only one variant affected MC4R-generated cAMP responses, although only a single concentration (1 μM) of αMSH was used in an endpoint assay (AlphaScreen)." (PMID 39807633, 2025). "Notably, in humans, mutations in the MC4R gene represent the most prevalent monogenic cause of severe early-onset obesity." (PMID 40419966, 2025). "Interestingly, MC4R remains the first cause of monogenic obesity, with an estimated prevalence of 5% and 2% in the obese pediatric and adult cohorts, respectively." (PMID 40822950, 2025). "Humans and rodents with genetic MC4R deficiency exhibit hyperphagic obesity." (PMID 41251447, 2025). "Inactivating mutations in the melanocortin 4 receptor (MC4R) gene cause monogenic obesity." (PMID 40674128, 2025). "Similarly, rs1942867 (MC4R) showed pleiotropic effects on HF and MI (P = 4.24 × 10−8), consistent with MC4R’s known role in energy homeostasis and obesity, both critical contributors to cardiac risk." (PMID 40630117, 2025). "Here we investigated lipid levels in men and women with obesity due to MC4R deficiency." (PMID 41102563, 2025). "We compared the frequency of mutations in GPR61 with MC4R to assess whether similar patterns of mutation frequency could be observed in the gene with the established role in obesity and metabolic disorders." (PMID 40133016, 2025).
Obesity (continued). "Thus, variants in BBS-associated genes can result in attenuation of MC4R signaling, causing hyperphagia and early-onset, severe obesity, which are characteristically distressing symptoms experienced by patients with BBS." (PMID 39919037, 2025). "The cumulative allele frequency is comparable to MC4R, which has a well-documented role in obesity." (PMID 40133016, 2025). "Importantly, in leukemia survivors, genetic variants in the FTO and MC4R genes, known for their roles in obesity and appetite regulation, affect weight and metabolic health." (PMID 41228239, 2025). "In humans, MC4R deficiency represents the commonest known monogenic obesity disorder." (PMID 39671021, 2025). "More specifically, 53 genes were associated with the “obesity-related traits” term (P = 6.09 × 10−11; adjusted P = 2.69 × 10−7) in the iHS analysis, including MC4R in South Bangladeshi river buffalo, mutations of which are the commonest form of monogenic obesity in humans." (PMID 40884803, 2025). "To date, approximately 30 distinct MC4R mutations have been associated with obesity." (PMID 40077044, 2025). "Therefore, while the relationship between the MC4R:c.216C>G variant and obesity in this case remains controversial, further functional and population studies are required to clarify its role." (PMID 40428329, 2025). "When investigating the causes of high BMI in adolescents, researchers have reported that monogenic obesity (e.g., MC4R mutations) and common genetic variants (e.g., the FTO gene) exert more pronounced effects during adolescence, possibly due to accelerated energy metabolism during puberty." (PMID 41334401, 2025). "Moreover, impairment of other signaling pathways including Gq and ERK1/2 pathways have been described for several obesity-associated MC4R mutations in cellular studies." (PMID 39807633, 2025). "Melanocrtin 4 receptor (MC4R) is critical for appetite and energy balance through hypothalamic signaling, where mutations often result in increased hunger and reduced satiety, contributing to obesity." (PMID 39769194, 2024). "More than 200 MC4R variants have been identified and associated with obesity." (PMID 38567654, 2024). "Previously, MC4R variants, such as H76R, have been identified in patients with obesity that displayed constitutive activity, although some of these variants could not be further stimulated with α-MSH." (PMID 38567654, 2024). "These GPCRs include melanocortin receptor-4 (MC4R), a central regulator of appetite, inactivating mutations of which are the most common genetic cause of obesity, and the receptor for ghrelin (growth hormone secretagogue receptor, GHSR), which enhances appetite." (PMID 39574659, 2024). "Before GWAS, MC4R deficiency was identified as the commonest monogenic form of obesity." (PMID 38279121, 2024). "Mutations in murine and human MC4R result in severe obesity." (PMID 38299666, 2024). "Loss of function (LoF) MC4R variants are the most common monogenic cause of obesity." (PMID 38567654, 2024). "MC4R gene polymorphisms were associated with obesity in Tibetan adults." (PMID 38279121, 2024). "Knowledge about the impact of a distinct MC4R variant on MC4R signaling may aid in selecting the best personalized obesity treatment option." (PMID 38567654, 2024). "Our results demonstrate the clinical importance of assessing the effect of MC4R variants on a range of molecular signaling mechanisms to determine their association with obesity, which may aid in improving personalized treatment." (PMID 38567654, 2024). "Pathogenic MC4R variants are the most common cause of monogenic obesity." (PMID 38567654, 2024). "Thus, mutations of the gene encoding for MC4R represent the most prevalent form of monogenic obesity, reaching up to 4% of all cases of severe obesity." (PMID 39876968, 2024). "In PHP 1a, obesity is associated with alterations in the MC4R pathway." (PMID 38397265, 2024).
Obesity (continued). "Analyses of whole-exome sequencing data identify rare loss-of-function variants in BSN associated with adult-onset obesity, type 2 diabetes and fatty liver disease, with stronger effect sizes than those observed for variants in known obesity risk genes such as MC4R." (PMID 38575728, 2024). "The C allele variant rs17782313 gene MC4R is thought to be a risk factor for obesity." (PMID 39458556, 2024). "We sought to gain more insight into the impact of these obesity-associated variants on various aspects of MC4R signaling: cell surface expression; total receptor expression; and α-MSH-induced cAMP production, β-arrestin-2 recruitment, and ERK pathway activation." (PMID 38567654, 2024). "Also in mice, homozygous deficiency of Mc4r results in severe obesity and hyperphagia, with heterozygous mice having an intermediate phenotype." (PMID 38567654, 2024). "Furthermore, there is now an extension trial for up to 5 years to study the safety and tolerability of continued setmelanotide in patients with obesity associated with genetic defects upstream of the MC4R in the leptin–melanocortin pathway." (PMID 39526054, 2024). "Setmelanotide, a highly selective MC4R agonist with a preferential Gqα/G11α pathway stimulation, is approved for specific causes of monogenic obesity upstream of the MC4R (pro-opiomelanocortin deficiency, proprotein convertase subtilisin/kexin type 1, leptin receptor deficiency)." (PMID 39104441, 2024). "MC4R variants represent the most common cause of monogenic obesity." (PMID 39526054, 2024). "Additionally, human genome association studies have identified genes linked to obesity and DM, such as the MC4R gene, which is crucial in regulating energy balance and appetite." (PMID 39605770, 2024). "Moreover, regulating the expression of obesity-causing genes, like MC4R, by using the CRISPRi technique gene expression has also been suggested to be useful in genetic obesity therapy." (PMID 38397265, 2024). "Most discovered MC4R mutations lead to a decrease in their function and result in obesity." (PMID 38397196, 2024). "For example, mutation in the leptin gene or its receptor that regulate hunger and satiety, and mutation in melanocortin-4 receptor (MC-4) or proopiomelanocortin genes may make an individual more prone to obesity." (PMID 38163110, 2024). "The MC4R haploinsufficient rat displayed a phenotypic expression of obesity, consistent with the mutation of the MC4R receptor as the most common human monogenic cause of obesity." (PMID 39741559, 2024). "However, they have already shown construct validity: mutations in Mc4r cause metabolic dysregulation and obesity in the major mammalian disease model, the mouse, and in a large cohort of human patients." (PMID 38299666, 2024). "Interestingly, MC4R mutations are the most frequent monogenic cause of obesity in humans, and common MC4R variants are linked to polygenic obesity in the general population." (PMID 38729350, 2024). "As haploinsufficiency of MC4R is the most common monogenic cause of obesity in humans, the study of melanocortin haploinsufficiency in the trajectory to obesity in the rat was considered of greater translational relevance than the study of homozygous knock-outs." (PMID 39741559, 2024). "We have identified 17 MC4R variants in adult and pediatric patients with obesity." (PMID 38567654, 2024). "Meta-analyses between the MC4R rs17782313 polymorphism and obesity indexes." (PMID 37621650, 2023). "Some in vitro studies showed that chemical chaperones and a newly FDA-approved drug, Setmelanotide (an MC4R agonist), could be used to treat some monogenic forms of obesity due to POMC, PCSK1, or LEPR deficiency." (PMID 38003551, 2023). "FTO and MC4R SNPs are associated with obesity, and urban living may accentuate the obesogenic effect of the FTO SNP." (PMID 37664850, 2023).
Obesity (continued). "Specifically, we found that inactivating Mrap2 specifically in MC4R-expressing neurons causes, like Mc4R loss-of-function, early-onset hyperphagia and obesity, whereas germline inactivation of Mrap2 caused a milder phenotype, with late-onset hyperphagia and obesity." (PMID 36692018, 2023). "Single gene like Melanocortin-4 receptor (MC4R) mutations blamed for obesity in many research." (PMID 37494308, 2023). "MC4R mutations are currently the leading monogenic cause of obesity." (PMID 37937009, 2023). "None of our polymorphisms is a missense variant that could alter the structure/function of the MC4R protein and explain the association described in this work with obesity biomarkers." (PMID 37508717, 2023). "However, MC4R variants of homozygous and mixed inheritance patterns have also been identified in consanguineous families and linked with severe obesity." (PMID 38002939, 2023). "Variants in the MC4R gene are the commonest cause of early-onset obesity in our population." (PMID 37329217, 2023). "Consequently, the obesity phenotype resulting from MC4R mutation can range from lean to morbid obesity." (PMID 38002939, 2023). "Recent studies aimed to improve the in vitro demonstration of MC4R variant LoF associated with obesity have investigated the efficiency of β-arrestin recruitment to MC4R compared with Gαs/cAMP accumulation or cyclic AMP response element (CRE)-reporter gene activation." (PMID 37040537, 2023). "The polymorphism rs17782313 near the MC4R (human melanocortin 4 receptor gene) was strongly associated with obesity in a large scale GWAS (genome wide association study), yet previous studies investigating its impact on AIWG did not lead to a definite conclusion regarding its effect." (PMID 36757449, 2023). "We found that carrying the MC4R rs17782313 is associated with obesity risk only in females." (PMID 38002939, 2023). "Thus, when three of the minor alleles in the variants of the MC4R gene included in the study were combined, a significant association with measures reflecting obesity (BMI and FMI) was found." (PMID 37508717, 2023). "In addition, 21 cases of patients with severe obesity carrying (likely) pathogenic homozygous variants in MC4R, from the same population, have been included for comparison." (PMID 37659411, 2023). "In summary, we identified two novel MC4R variants in patients with severe obesity." (PMID 38003551, 2023). "In human, mutations in MC4R are the most common cause of early-onset obesity." (PMID 38027153, 2023). "In 1997, the hypothesized function of this receptor was validated in mice studies, and in 1998, human genetic studies revealed that MC4R genetic mutations could lead to monogenic obesity." (PMID 37937009, 2023). "MC4R's appetite-reducing effect, secondary to the promotion of satiety and energy use, makes it an ideal therapeutic target; setmelanotide is especially beneficial for individuals with obesity related to POMC or MSH deficiency." (PMID 37937009, 2023). "MC4R variants were the most common cause of monogenic obesity in our cohort." (PMID 37329217, 2023). "Since MC4R and MRAP2 are essential for suppressing feeding behavior and since MC4R fails to localize to primary cilia in Mrap2–/– mice, it is likely that the failure of MC4R to localize to cilia accounts for the obesity observed in MRAP2-deficient mice and humans." (PMID 36692018, 2023). "Pathogenic mutations affecting the gene MC4R (18q21.32) can be considered as the greatest risk factors for the co-occurrence of obesity and T2D, with MC4R deficiency being the most common genetic cause of obesity, affecting nearly five percent of all obese children." (PMID 37512517, 2023). "Overall, the obesity risk allele in the MC4R rs17782313 may beneficially affect the decrease of adiposity in short-term pediatric therapeutic interventions, either individually or as part of a GRS, possibly through a sex-specific interaction." (PMID 36986146, 2023).
Obesity (continued). "In conclusion, this case report demonstrates that naltrexone-bupropion treatment can effectively reduce weight and improve patient-reported hyperphagia and quality of life in the long term in a patient with severe obesity and hyperphagia due to MC4R deficiency." (PMID 36876127, 2023). "The loss of basal activity in MC4R mutations is considered to be one cause of obesity." (PMID 37627313, 2023). "Heterozygous loss-of-function mutations in MC4R are the most common monogenic form of obesity." (PMID 36943057, 2023). "These cells play a key role in the control of food intake and energy balance, and the disruption of this circuit by changes in leptin sensitivity or mutations in the genes encoding leptin, the leptin receptor, POMC, or MC4R, amongst other genes in this system, can lead to severe obesity." (PMID 36674935, 2023). "MC4R rs17782313 variant has also been associated with other metabolic processes that could indirectly contribute to obesity." (PMID 38002939, 2023). "Moreover, MC4R gene variation can interact with other obesity-linked genes and thereby elevate obesity risk." (PMID 38002939, 2023). "It is worth noting that one MC4R agonist (Setmelanotide) has been approved for use in patients with obesity, but it can only be prescribed to patients who are confirmed to have obesity-causing gene mutations in the melanocortin pathway instead of general obesity." (PMID 37069175, 2023). "Consequently, pathogenic variants in the MC4R gene can lead to severe early-onset obesity and hyperphagia and the diagnosis of genetic obesity." (PMID 36876127, 2023). "MC4R has, over time, been associated with eating behaviour, so much so that variants of the gene coding for MC4R represent the most frequent cause of monogenic obesity." (PMID 37508552, 2023). "Our analyses highlighted several candidate genes, such as CNTN1—which has been linked to weight loss in mice and is potentially influential for AGE100—and MC4R, which is associated with obesity and appetite and may impact both traits." (PMID 37372438, 2023). "Therefore, the MC4R gene and its polymorphisms appear to be an important factor to consider in the evaluation of genetic predisposition to obesity and comorbidities, even in childhood." (PMID 37508717, 2023). "Although it is clear that MC4R gene polymorphisms are related to obesity characteristics, it is interesting to note how different SNPs may have different effects on the metabolism of individuals." (PMID 37508717, 2023). "Moreover, two SNPs in the noncoding parts of TNF gene have been shown to be important for polygenic obesity in Labrador retriever dogs, whereas two exonic SNPs in the MC4R gene have been linked to body weight in Beagle dogs." (PMID 37799139, 2023). "In humans, different mutations in MC4R have a major gene effect in obesity." (PMID 37025415, 2023). "The identification of MC4R rs17782313 as a significant risk factor for obesity, particularly among females, could pave the way for more targeted interventions." (PMID 38002939, 2023). "Liraglutide, a glucagon-like peptide receptor agonist (GLP1-RA), shares high amino acid sequence homology with GLP-1, was first approved for type 2 diabetes and later approved for treatment of common obesity; it reduces appetite and leads to weight loss in obesity caused by MC4R pathogenic variants." (PMID 37329217, 2023). "Mutations in MC4R accounted for 3–5% of all severe human obesity cases." (PMID 37571382, 2023). "Furthermore, the gene MC4R—which has been linked to obesity and appetite—emerged as a possible determinant affecting both traits." (PMID 37372438, 2023). "We report the long-term response to bariatric surgery in a singular family of four adolescents with severe obesity (41-82 kg/m2), homozygous for the C271R loss-of-function mutation in the melanocortin 4 receptor (MC4R), and three adults heterozygous for the same mutation." (PMID 35629934, 2022).